EIF5A2 (eukaryotic translation initiation factor 5A2)
Diseases named in the same sentence as EIF5A2 in open-access papers (continued):
Sharing a sentence is not in itself a finding about the gene and the disease.
cancer (63 papers, 2011 to 2025). A tumor composed of atypical neoplastic, often pleomorphic cells that invade other tissues. "While eIF5A2 is known as oncogene, more directly associated with oncogenic processes, including invasion, metastasis, and drug resistance in cancer." (PMID 40040695, 2025). "Hypoxia also induces eIF5A2 (encoding eukaryotic translation initiation factor 5 A) expression, which is an oncogene located at 3q26 associated with progression in various cancers, including NSCLC, bladder cancer, and colorectal cancer (CRC)." (PMID 35931669, 2022). "Overexpression of eukaryotic initiation factor- 5A2 (eIF5A2) has been implicated in promoting tumor cell migration and invasion in many cancers." (PMID 32522053, 2020). "On the contrary, eIF5A-2 is highly expressed in many cancers and its overexpression in certain cell types causes cellular transformation, for which it has been proposed to act as an oncogene." (PMID 33379337, 2020). "Both eIF5A isoforms have been linked to cancer functions, though, given the weak or undetectable expression of eIF5A2 in most tissues, their overexpression in various cancers is more readily identified." (PMID 29799508, 2018). "These new mouse lines represent excellent in vivo models to study hypusine-dependent biological processes, hypusination-related disorders caused by eIF5A1 and eIF5A2 gene aberrations and mRNA expression dysregulation as well as several major human cancer types and potential therapies." (PMID 36848144, 2023). "The major form, eIF5A1, is abundantly expressed in most types of normal cells and tissues, while eIF5A2 is undetectable but usually overexpressed in many types of cancer and closely associated with tumor growth, epithelial–mesenchymal transition (EMT), metastasis, recurrence, and poor prognosis." (PMID 37653021, 2023). "We next addressed whether high eIF-5A levels were associated with bad prognosis in LUAD and found that cancer patients with high EIF5A2 levels showed poorer prognosis than the rest of patients." (PMID 36915194, 2023). "The eIF5A2 gene resides in chromosome 3q26, a region frequently amplified in various human cancers and eIF5A2 overexpression has been associated with certain human cancers." (PMID 34273022, 2022). "The overexpression of EIF5A2 was associated with invasion, metastasis, and other malignant phenotypes of various cancers, suggesting that EIF5A2 may be a potential therapeutic target." (PMID 34796198, 2021). "Research has shown that EIF5A2 is elevated in multiple cancers, including cervical, ovarian, colorectal, gastric, liver, melanoma, lung, nasopharyngeal, gallbladder, and esophageal squamous cell carcinoma." (PMID 40964657, 2025). "This compound has demonstrated significant efficacy in preclinical models, highlighting the importance of developing specific inhibitors that effectively target EIF5A2 in cancer therapy." (PMID 41358199, 2025). "The upregulation of eIF5A2 expression mediated by hypoxia, reactive oxygen species-related pathways, and TGFβ signaling exacerbates cancer prognosis." (PMID 40617352, 2025). "We discovered that eIF5A2, regulated by polyamines, and miR-6514-5p play a major role in cancer cell growth, and the individual genes whose expression was upregulated by eIF5A2 were distinct from those whose expression was upregulated by eIF5A1." (PMID 40617352, 2025). "We analyzed the expression, prognosis, and mutation of EIF5A2 and its relationship with TMB and MSI in pan-cancers." (PMID 40964657, 2025). "In this study, we examined EIF5A2 expression, prognosis, clinicopathological characteristics, and immunity from a pan-cancer perspective." (PMID 40964657, 2025). "What’s more, eIF5A1 and eIF5A2 are known as critical players in the regulation of translation and cellular metabolism, especially in cancer biology." (PMID 40040695, 2025).
cancer (continued). "Unlike EIF5A1, which is typically expressed in normal humans, EIF5A2 has tissue-specific and cell-specific characteristics, and its mRNA is expressed only in specific tissues (such as testes, brains, and some malignant tumors) and their cells." (PMID 40964657, 2025). "EIF5A2 expression correlates with immune cell infiltration and immune checkpoints in several cancers." (PMID 40964657, 2025). "As a key translation factor, EIF5A, and in particular its isoform EIF5A2, is overexpressed in various cancers." (PMID 40959079, 2025). "Some studies suggest that eIF5A2 facilitates cancer cell protrusions and invasive capacity by activating the translation of key proteins." (PMID 40040695, 2025). "Subsequently, The Cancer Genome Atlas (TCGA) and the Gene Expression Profiling Interactive Analysis (GEPIA) databases were employed to validate EIF5A2 expression across various cancer types." (PMID 38770178, 2024). "Our results demonstrated that the expression of EIF5A2 was significantly different in 27 types of cancers (p < 0.05) compared to healthy tissues." (PMID 38770178, 2024). "In cancer biology, the aberrant overexpression of eukaryotic translation initiation factor 5A2 (EIF5A2) has been correlative with an ominous prognosis, thereby underscoring its pivotal role in fostering metastatic progression." (PMID 38770178, 2024). "Elevated EIF5A2 levels have been detected in various cancers, where it promotes cancer spread and presents as a promising target for cancer treatment." (PMID 38770178, 2024). "Our research endeavors were thus aimed at elucidating the utility and significance of EIF5A2 as a robust indicator of cancer outcome prediction." (PMID 38770178, 2024). "The results showed that the overexpression of EIF5A2 was associated with poor OS in three types of cancer (p < 0.05) and worse DFS and PFS in two and six cancer types (p < 0.05)." (PMID 38770178, 2024). "Analysis of patient datasets identified EIF5A2 amplifications in many types of human cancer, including the prostate." (PMID 38654106, 2024). "The eIF5A2 gene showed a markedly different pattern in cancer, with six tumor types exhibiting more than 5% frequency of eIF5A2 aberrations." (PMID 36848144, 2023). "siEIF5A2 was chosen for targeting and knocking down the oncogene eukaryotic translation initiation factor 5A2 (EIF5A2), thus inhibiting cancer cell growth." (PMID 37351161, 2023). "In T24 cells, Mg(II)-Cat/siEIF5A2 successfully down-regulated the gene expression of EIF5A2 and induced cancer cell apoptosis." (PMID 37351161, 2023). "We have scored the presence of genetic alterations of EIF5A1 and EIF5A2 in LUAD data sets from TCGA with cBioportal for Cancer genomics." (PMID 36915194, 2023). "We have also analysed the effects of genetic silencing of eIF-5A1 and eIF-5A2 isoforms in LUAD cells to study their contribution to cancer progression." (PMID 36915194, 2023). "Among them, EIF5A1 plays different functions in various cancers, possibly as a tumor-suppressor or oncogene, while EIF5A2 promotes the occurrence and development of cancer." (PMID 37047039, 2023). "All together, these data suggest that eIF-5A1 and eIF-5A2 have different impact on cancer cell proliferation, migration and cytoskeleton rearrangements." (PMID 36915194, 2023). "Meanwhile, research on EIF5A2 mainly focuses on the field of cancer, which shows that EIF5A2 can promote the development of a variety of cancers, such as bladder cancer, cervical cancer, and colorectal cancer." (PMID 37047039, 2023). "eIF-5A2 was expressed in the cytoplasm, nucleus and perinucleus of carcinoma cells, while in adjacent normal lung samples eIF-5A2 immunological signal was strongly reduced and limited to the cytoplasm of alveolar walls and alveolar macrophages." (PMID 36915194, 2023). "For example, it was reported that EIF5A2 was involved in maintaining the existence of cancer stem cells in HCC cells through the c-Myc pathway." (PMID 36290289, 2022).
cancer (continued). "Then, a pan-cancer analysis of EIF5A2 in the TCGA database indicated that EIF5A2 was highly expressed in various tumor tissues, including HCC." (PMID 36290289, 2022). "EIF5A2 plays an important role in many biological processes, including tumor formation, cancer cell growth, maintenance of cancer stem cells and EMT process." (PMID 35444536, 2022). "Specifically, EIF5A2 isoform has been shown to promote the epithelial-mesenchymal transition in several types of cancer cells." (PMID 35163207, 2022). "EIF5A1 is ubiquitously expressed in all mammalian tissues and cell types, whereas EIF5A2 shows restricted expression in healthy tissue (being almost undetectable) but is overexpressed in certain tissues or cancer cells." (PMID 35163207, 2022). "EIF5A2 can initiate tumor formation, promote cancer cell growth, and increase cancer cell movement and metastasis by inducing EMT." (PMID 35309319, 2022). "This characteristic has stimulated considerable attention from a therapeutic perspective for various types of cancer in which the paralog eIF5A2 is strongly expressed." (PMID 34952646, 2021). "Eukaryotic initiation factor 5A2 (EIF5A2) is highly expressed in a variety of human cancers but rarely expressed in normal tissues." (PMID 33827661, 2021). "Accumulating evidences show that EIF5A2 plays important roles in enhancing anchorage-independent growth, xenograft tumor growth, increasing cancer cell metastasis, and promoting treatment resistance through multiple pathways." (PMID 33726845, 2021). "As many publications have focused on eIF5A2 and its relationship with cancer, this review will be mainly dedicated to eIF5A1." (PMID 34952646, 2021). "Multiple types of human cancers present aberrant expression of EIF5A2, which is critical for tumor growth, metastasis, and treatment resistance." (PMID 33726845, 2021). "eIF5A2 regulates EMT in several cancers, and contributes to invasiveness and chemo-resistance of tumors." (PMID 34864817, 2021). "The cellular processes which can be regulated by eIF5A2 in HCC including maintenance of cancer stem cells, metabolic reprogramming, EMT, and reorganization of actin cytoskeleton." (PMID 32368188, 2020). "In contrast to eIF5A, the expression of the other isoform (eIF5A-2) was detected only in specific tissues (testis and brain) or in various cancer types including colon, ovarian, bladder and liver." (PMID 32235505, 2020). "It is worthy to note that our findings highlight that the crucial miR-9/eIF5A2 axis enhances the anti-cancer effect of doxorubicin through regulating autophagy in PDAC cells." (PMID 31938057, 2020). "The expression of eIF5A2 is up-regulated in a variety of malignant tumor tissues, and the up-regulation of eIF5A2 is related to the poor prognosis of the patients with malignant tumors." (PMID 33200656, 2020). "Numerous evidence demonstrated that enforced eIF5A2 enhances cancer cell growth, increases cancer cell metastasis, and promotes chemotherapy resistance through multiple means." (PMID 32522053, 2020). "Basic research and clinical evidence show that eIF5A2 gene amplification has been shown in many cancer tissues and cell lines." (PMID 33200656, 2020). "Meanwhile, eIF5A2 is overexpressed in many cancers, and plays an important role in the development and progression of cancers." (PMID 32368188, 2020). "Our current studies provides a new and promising anti-cancer approach by using of PL-1/miR-9 nanoparticles and demonstrate miR-9/eIF5A2 as a new potential drug target for future synergic therapy against PDAC." (PMID 31938057, 2020). "Enhanced eIF5A2 expression correlates with poor prognosis and poor response for chemotherapeutic drugs in patients with cancers, suggesting that eIF5A is a useful biomarker in the prediction of cancer prognosis and drug response." (PMID 33200656, 2020). "EIF5A2 was identified as an oncogene, and in recent years, a growing amount of research has confirmed that EIF5A2 is involved in cancer development and progression." (PMID 32368188, 2020).
cancer (continued). "In CRC, higher EIF5A2 expression was correlated with aggressive characteristics of cancers and poor survival of patients." (PMID 32368188, 2020). "Overexpression of EIF5A2 has been observed in several cancers with less favorable clinical features and outcomes." (PMID 32605067, 2020). "The expression of eIF5A2 is critically required for the proliferation of some transformed cells; in particular, carcinoma cells." (PMID 31938057, 2020). "eIF5A2 overexpression in cancer cells is correlated to prognosis factors of tumor metastasis and venous infiltration." (PMID 28083147, 2016). "Previous studies have shown that eIF5A2 eliminates the augmentation of carcinoma cell migration, invasion, and the EMT through down-regulating MTA1 (metastasis-associated 1)." (PMID 27028999, 2016). "Eukaryotic translation initiation factor 5A2 (eIF5A2), one of the two isoforms in the eIF5A family, has been reported to be a new oncogene in many types of human cancer." (PMID 26581310, 2015). "Our results indicated that EIF5A2 overexpression enhanced the stemness of the 510-eIF5A2 cells and induced multiple cancer stem cell markers." (PMID 26317793, 2015). "More interestingly, in the current study, EIF5A2 overexpression was also found in invading cancer cells (vessel invasion), and overexpression of EIF5A2 protein in primary GC tissue correlated with the presence of lymphovascular invasion." (PMID 25793713, 2015). "eIF5A2, an essential component of translation elongation, has been identified to be a novel oncogenic protein in many types of human cancer." (PMID 26581310, 2015). "The eIF5A-1 isoform is expressed at high levels in all tissues, although the eIF5A-2 isoform is detectable only in some embryonic tissues, adult testis, central nervous system and cancer tissue." (PMID 24832488, 2014). "Examples of genes amplified on DMs include MYCN in neuroblastoma, C-MYC in colon cancer cells, EGFR in gliomas, and eIF-5A2 in ovarian cancer cells, and all of which when lost via DMs contributes to reversal of the cancer phenotype." (PMID 23991020, 2013). "While for eIF5A2, the gene resides on a genetically unstable chromosome whose amplification is frequently observed in various cancers." (PMID 23029619, 2012). "Eukaryotic translation initiation factor 5A (eIF5A) is one of the eIFs involved in translation initiation and eIF5A2, one of its isoforms, is upregulated in various cancers including HCC as a result of chromosomal instability, where it resides." (PMID 23029619, 2012). "Functional study has demonstrated the oncogenic role of eIF-5A2 in the initiation and progression of human cancers." (PMID 21612665, 2011). "Alcohol intoxication, an efficient way to induce liver tumorigenesis in cancer-prone rodents, was used to induce liver lesions in 12-week-old eIF-5A2 transgenic mice (n = 20) and wild-type littermates (n = 12)." (PMID 21612665, 2011). "In this study, EIF5A2 expression, prognosis, mutation, and its relationship with tumor mutation burden (TMB), microsatellite instability (MSI), immunity, and drug sensitivity were studied from a pan-cancer perspective." (PMID 40964657, 2025). "Unlike the MethSig cancer genes with an MR/MN smaller than 1, three of the 52 MethSig cancer genes with an MR/MN greater than 1 (CYP4F2, MSC and EIF5A2) were associated with worse survival in a multivariate Cox analysis (P = 0.022 for CYP4F2, P = 0.02 for MSC and P = 0.011 for EIF5A2)." (PMID 40931149, 2025). "However, eIF5A2 has become increasingly recognized as an oncogene in cancer development and progression." (PMID 40617352, 2025). "eIF5A1 is ubiquitously expressed in all tissues and is essential for normal cell growth, whereas eIF5A2 is often expressed in human cancer tissues; however, the functional differences between eIF5A1 and eIF5A2 remain unclear." (PMID 40617352, 2025).
cancer (continued). "Based on these observations, we propose that polyamine-led glycolysis activation during cancer progression is based on the combination of altered gene expression via structural changes in specific mRNAs and the increased eIF5A2 translation elongation, both regulated by polyamines." (PMID 40617352, 2025). "EIF5A2 may serve as a potential prognostic marker and a latent focus for cancer immunological treatment." (PMID 40964657, 2025). "Our findings reveal an important role for eIF5A2, regulated by polyamines and miR-6514-5p, in cancer cell proliferation, suggesting that the interaction between eIF5A2 and ribosomes, which regulate cancer progression, is a selective target for cancer treatment." (PMID 40617352, 2025). "Our findings reveal that eIF5A2, regulated by polyamines and miR-6514-5p, participates in the translational machinery that is adapted to cancer progression and that this can be targeted for cancer treatment." (PMID 40617352, 2025). "The patients were divided into EIF5A2 high and low expression groups based on the median value, and the results confirmed that EIF5A2 overexpression was linked to shorter OS and DFS in patients with cancer." (PMID 38770178, 2024). "To further confirm our findings, we investigated if EIF5A2 could serve as a prognostic biomarker across various types of cancer." (PMID 38770178, 2024). "In addition, the fact that eIF-5A2 knock-out mouse were viable and had normal development made eIF-5A2 a very attractive therapeutic target in cancer." (PMID 36915194, 2023). "Moreover, elevated eIF5A2 expression carries unfavorable prognostic implications for several cancer and both eIF5A1 and eIF5A2 have been advanced as cancer biomarkers, thus further expanding the potential use for our new mouse models." (PMID 36848144, 2023). "However, eIF5A2 overexpression plays an important role in a variety of cancers, with particularly high expression in colorectal adenocarcinoma." (PMID 36848144, 2023). "However, while eIF-5A1 is abundant and ubiquitously expressed in most tissues and cells, eIF-5A2 is rarely expressed in most tissues except in brain and testis, and it is overexpressed in several human cancers." (PMID 36915194, 2023). "However, the regulation of eIF-5A2, its modification by hypusination and its functional role as translation factor in cancer cells undergoing migration and invasion is still poorly understood." (PMID 36915194, 2023). "Since eIF-5A2 is not widely expressed in normal tissue and its overexpression is associated with cancer, it has been postulated as a marker of bad prognosis and more aggressive stage of the disease." (PMID 36915194, 2023). "EIF5A2 also induces autophagy, leading to chemotherapy resistance in various cancers." (PMID 35931669, 2022). "Therefore, EIF5A2 is an attractive drug target for cancer therapy based on its aberrant expression in various cancer types." (PMID 33827661, 2021). "The human eIF5A1 gene resides on 17p12-p13 and the eIF5A1 protein is ubiquitously expressed in almost all cells and tissues, whereas the eIF5A2 gene resides on chromosome 3q25-q27 and its expression is mainly found in testis, brain, and cancer cell lines and tissues." (PMID 34952646, 2021). "Vertebrates possess another gene encoding eIF5A2, which expresses less and is not crucial for the body; however, eIF5A2 has been found in various cancer cells, responsible for poor prognosis and rapid growth." (PMID 34207607, 2021). "Eukaryotic translation initiation factor 5A2 (eIF5A2), an isoform of eIF5A, plays an essential role in mRNA translation, and is an oncogene that regulates cell proliferation, invasion, metastasis, and cancer progression in several cancers." (PMID 34864817, 2021). "There is accumulating evidence that eIF5A2 could regulate invasion and migration in different cancers." (PMID 34864817, 2021). "Interestingly, we found that EIF5A2, a vital gene for cancer drug resistance, was predicted as a potential target gene of miR‐383." (PMID 30801960, 2019).